SNORD114-27 (small nucleolar RNA, C/D box 114-27)
Synonyms: 14q(II-27)
Gene: Small nucleolar RNA gene on chromosome 14 (100,988,161 to 100,988,230, forward strand). Ensembl gene ENSG00000200636.
Gene Ontology:
Biological process: RNA processing
Cellular component: nucleolus
Homologues: Orthologues: chimpanzee SNORD114-27 (99% identical), macaque SNORD114-27 (91% identical). Paralogues in human: SNORD114-23 (89% identical), SNORD114-18 (83% identical), SNORD114-20 (83% identical), SNORD114-21 (83% identical), SNORD114-28 (83% identical), SNORD114-3 (83% identical), SNORD114-5 (83% identical), SNORD114-9 (83% identical), SNORD114-11 (81% identical), SNORD114-15 (81% identical), SNORD114-22 (81% identical), SNORD114-25 (81% identical), and 26 more.